AOX1 (aldehyde oxidase 1)
Description:
Oxidase with broad substrate specificity, oxidizing aromatic azaheterocycles, such as N1-methylnicotinamide, N-methylphthalazinium and phthalazine, as well as aldehydes, such as benzaldehyde, retinal, pyridoxal, and vanillin. Plays a key role in the metabolism of xenobiotics and drugs containing aromatic azaheterocyclic substituents. Participates in the bioactivation of prodrugs such as famciclovir, catalyzing the oxidation step from 6-deoxypenciclovir to penciclovir, which is a potent antiviral agent. Is probably involved in the regulation of reactive oxygen species homeostasis. May be a prominent source of superoxide generation via the one-electron reduction of molecular oxygen. May also catalyze nitric oxide (NO) production via the reduction of nitrite to NO with NADH or aldehyde as electron donor. May play a role in adipogenesis.
Synonyms: AO; AOH1
Tractability: Small molecule: a structure with a bound ligand is known; a high-quality ligand is known; it belongs to a druggable protein family. PROTAC: ubiquitination databases record sites on it; its protein half-life has been measured; a small molecule that binds it is known.
Target class: Enzyme; Oxidoreductase
Gene: Protein-coding gene on chromosome 2 (200,585,864 to 200,677,064, forward strand). Ensembl gene ENSG00000138356.
Subcellular location: Cytoplasm
Subcellular location (Human Protein Atlas): Cytosol; Cytokinetic bridge; Microtubules; Nuclear bodies
Pathways (Reactome):
Metabolism: Vitamin B6 activation to pyridoxal phosphate
Gene Ontology:
Molecular function: 2 iron, 2 sulfur cluster binding; aldehyde oxidase activity; aryl-aldehyde oxidase activity; flavin adenine dinucleotide binding; identical protein binding; iron ion binding; molybdopterin cofactor binding; oxidoreductase activity, acting on CH or CH2 groups, oxygen as acceptor; oxidoreductase activity, acting on the aldehyde or oxo group of donors, oxygen as acceptor; protein homodimerization activity; FAD binding; iron-sulfur cluster binding; metal ion binding; NAD binding; oxidoreductase activity; pyridoxal oxidase activity
Biological process: xenobiotic metabolic process
Cellular component: cytosol; extracellular exosome; cytoplasm
Genetic constraint (gnomAD): Loss-of-function variants: 106 observed, 123.51 expected, observed/expected ratio (o/e) 0.86, 90% interval 0.73 to 1.01. The upper end of that interval is the gene's LOEUF score, 1.01, which puts it in group 4 of 6, group 1 being the genes least tolerant of losing a copy. Missense variants: 1,330 observed, 1,410.5 expected, observed/expected ratio (o/e) 0.94, 90% interval 0.9 to 0.99. Synonymous variants: 454 observed, 502.66 expected, observed/expected ratio (o/e) 0.9, 90% interval 0.84 to 0.98.
Homologues: Orthologues: chimpanzee AOX1 (99% identical), macaque AOX1 (96% identical), pig AOX1 (84% identical), mouse Aox1 (83% identical), rabbit AOX1 (83% identical), rat Aox1 (82% identical), guinea pig AOX1 (75% identical), tropical clawed frog aox1 (60% identical), zebrafish aox6 (55% identical), Drosophila melanogaster ry (44% identical), Caenorhabditis elegans xdh-1 (42% identical). Paralogues in human: XDH (50% identical).
Diseases named in the same sentence as AOX1 in open-access papers:
AOX1 is named in the same sentence as 68 diseases in open-access papers, as found by Europe PMC text mining. Sharing a sentence is not in itself a finding about the gene and the disease. The quoted sentences say what the papers report.
prostate carcinoma (19 papers, 2012 to 2026). A carcinoma that arises from epithelial cells of the prostate gland. "This is consistent with a prior GWAS identifying a common variant at the AOX1 locus, which was associated with prostate-cancer-specific survival time, and with AOX1 expression levels that correlated with disease recurrence." (PMID 39971927, 2025). "Two recently published studies identified several genes—BIK, SAMHD1, FAM111A, AOX1, among others—in which rare variants are significantly and strongly associated with increased risk of prostate cancer (PCa) and its aggressiveness." (PMID 40825105, 2025). "The possible prostate cancer (PCa) diagnostic biomarkers AOX1, APOC1, ARMCX1, FLRT3, GSTM2, and HPN were identified and validated using the GSE69223 and GSE71016 datasets." (PMID 37583929, 2023). "However, the SNP rs73055188 at the AOX1 locus is related to the survival time of prostate cancer, and lower expression of AOX1 is associated with early biochemical recurrence events." (PMID 35813821, 2022). "In our study, we identified AOX1, APOC1, ARMCX1, FLRT3, GSTM2, and HPN as biomarkers associated with prostate cancer (PCa)." (PMID 37583929, 2023). "AOX1 is a DNA methylation marker for prostate cancer, and hypermethylation leads to AOX1 inhibition." (PMID 36300097, 2022). "This SNP was found to be associated with prostate-cancer-specific survival time, while lower AOX1 gene expression was correlated with shorter time to recurrence of prostate cancer." (PMID 34073600, 2021). "Expression of AOX1 is decreased in prostate cancer, when compared to normal prostate tissue, and is negatively correlated with Gleason score." (PMID 34073600, 2021). "If validated, this implies a role for AOX1 in prostate cancer progression, but no substantial impact on the overall risk of disease development." (PMID 39971927, 2025). "Further studies would be needed to see if AOX1 acts similarly in prostate cancer." (PMID 38173042, 2024). "Also, the AOX1 CpG island methylation is highly detected in prostate cancer and can be used as a prognostic signature." (PMID 35813821, 2022). "In this study, we show that prostate cancer-specific hypermethylation of the eight genes AOX1, CCDC181 (C1orf114), GABRE, GAS6, HAPLN3, KLF8, MOB3B, and SLC18A2 can be detected by qMSP with very high sensitivity and specificity in scarce prostate needle biopsy samples taken at the time of diagnosis." (PMID 28084441, 2017). "Interestingly, AOX1 converts 5-hydroxyindoleacetaldehyde to 5-hydroxyindoleacetate, which is a significantly down-regulated metabolite in metastatic prostate cancers compared to primary tumor samples." (PMID 23119026, 2012). "AOX1(aldehyde oxidase 1), a broad-spectrum oxidase, has demonstrated potential as a biomarker in various cancers, where its low expression in clear cell renal cell carcinoma and prostate cancer correlates with poor prognosis, suggesting its tumor-suppressing capabilities." (PMID 39975557, 2025). "For example, loss of AOX1 expression by epigenetic regulation could promote bladder cancer via metabolic deregulations; the SNP rs73055188 of AOX1 locus is related to prostate cancer survival time, and AOX1 gene expression level is correlated with recurrence of prostate cancer." (PMID 33135729, 2020). "Our results align with recent studies that have found AOX1 to be hypermethylated in prostate cancer; however, the effect of decreased AOX1 expression in prostate cancer has not been studied." (PMID 38173042, 2024). "Through the analysis of seven datasets (TCGA, GSE30521, GSE4602, GSE55945, GSE69223 GSE104131, and GSE200879), we identified two upregulated genes (AMACR and GCNT1) and seven downregulated genes (TGFB3, SRD5A2, PGM5, HOXD10, AOX1, HSPB6, and SNAI2) in prostate cancer compared to normal tissue." (PMID 38374143, 2024). "Similarly, the hypermethylation of AOX1 (aldehyde oxidase 1) and GSTP1 (Glutathione S-transferase 1) in prostate cancer also lead to the silence of gene expression." (PMID 25774687, 2015).
xanthinuria (11 papers, 2012 to 2025). A metabolic metabolic disorder characterized by excess urinary excretion of the purine base xanthine. "AOX1 is a candidate gene for amyotrophic lateral sclerosis, and upregulated enzyme levels have been implicated in xanthinuria, cancer, and diabetes through OS activation." (PMID 34545296, 2021). "AOX1 is involved in the regulation of reactive oxygen species homeostasis and has been associated to hereditary xanthinuria." (PMID 31075877, 2019).
bladder cancer (7 papers, 2020 to 2025). "The synthetic lethality of DNA-PKcs and AOX1 identified in this study also suggests a potential treatment for bladder cancer with epigenetic loss of AOX197 using DNA-PKcs inhibitors." (PMID 41372233, 2025). "Bladder cancer progression was recently linked to the epigenetic silencing of the aldehyde oxidase gene (AOX1) by the methyltransferase EZH2." (PMID 35681770, 2022). "Loss of AOX1 in advanced bladder cancer also leads to alteration in metabolism, consistent with our findings in ccRCC." (PMID 34290740, 2021). "Similarly, loss of AOX1, probably linked to its hypermethylated promoter, contributes to the transition from low-grade to high-grade during bladder carcinoma progression, thereby promoting invasion and metastasis." (PMID 38589501, 2024). "Loss of AOX1 in advanced bladder cancer promoted cancer progression, and AOX1-related metabolites predicted advanced bladder cancer." (PMID 34290740, 2021). "A previous study reported downregulation of AOX1 in advanced bladder cancer due to methylation modification by EZH2." (PMID 34290740, 2021). "Aldehyde oxidase 1 decreases the metabolic level and displays tumor inhibition activity in bladder cancer, whereas long intergenic non-coding RNA-nucleotide metabolism regulator upregulates nucleotide metabolism and increase the proliferation of tumor cells." (PMID 33324566, 2020). "As AOX1 silencing enhances the bladder cancer cell transformation potential and increases their invasive properties through EMT invasion, activation of kynurenine might contribute to bladder cancer aggressiveness." (PMID 35681770, 2022).
type II xanthinuria (5 papers, 2012 to 2025). "Notably, although the serum and urine levels of xanthine and hypoxanthine as well as the activity of XDH, AOX1, and MOCOS are important diagnostic criteria for Xanthinuria type II, these tests cannot be performed in most hospital laboratories." (PMID 41164817, 2025).
breast carcinoma (4 papers, 2021 to 2025). "Our findings suggest a second mechanism in which breast cancer cells, which are often deficient in the HR genes BRCA1/2, are killed due to synthetic lethality of raloxifene-induced inhibition of AOX1." (PMID 41372233, 2025). "Furthermore, it was shown that a relationship exists between Aox1 and breast cancer, and a previous study reported that this factor is down-regulated in breast cancer cells." (PMID 35180880, 2022). "It has been reported that AOX1 inhibited the development of breast cancer, but at the same time, it could promote prostate and rectal cancers." (PMID 33803640, 2021).
COVID-19 (4 papers, 2021 to 2024). A disease caused by infection with severe acute respiratory syndrome coronavirus 2. "Endogenously caused NAD+ deficiency, common in old age and other predisposing conditions for development of serious COVID-19, most likely stems from elevated NAD+ degradation in NAD+-consuming reactions, coupled with NAD+ salvage pathway stalling, mediated by cooperative activity of NNMT and AOX1." (PMID 35457123, 2022). "Salmeterol targets on seven non-n-COV host proteins (ADRB1, ADRB2, ADRB3, AOX1, DRD3, KCNH2, and THPO), meaning that it may not act on COVID-19 via directly targeting COV host proteins." (PMID 34539756, 2021).
diabetes (4 papers, 2009 to 2024). "Diabetes and inflammatory mediators, including hs-CRP, have also been implicated in AOX1 activity, as well as HDL-cholesterol-levels via interaction of AOX1 with the ATP-binding cassette transporter A1 (ABCA1) which is a regulator of HDL metabolism." (PMID 32041099, 2020).
glioma (4 papers, 2022 to 2025). A benign or malignant brain and spinal cord tumor that arises from glial cells (astrocytes, oligodendrocytes, ependymal cells). "Immune-related pathways such as TNF signalling (IDH3B/G, MDH1, ACO2, SDHA, OGDHL) and JAK/STAT3 (PIAS2/3, PTPN2, AKT1/2, MCL1, CISH, AOX1) signalling are enriched in gliomas and play a critical role in their progression." (PMID 41007296, 2025). "Six genes of these essential TrMGs, including MAOB, HSD17B10, KYNU, AOX1, and OGDH, were determined as hazardous factors for glioma patients, and other two genes (CYP2E1 and ALDH2) were identified as protective factors." (PMID 36386216, 2022).
Hepatic steatosis (4 papers, 2009 to 2025). Steatosis is a term used to denote lipid accumulation within hepatocytes. "Fatty liver pathogenesis is associated with elevated liver AOX1, while adiponectin can inhibit the expression of AOX1 by activating PPARɑ, therefore enhancing the lipid oxidation, attenuating the inflammation reaction and alleviating the liver injuries." (PMID 34481473, 2021). "On the contrary, following TRF intervention, the expression of hepatic AOX1 was restored to normal levels, accompanied by a decline in circulating levels of N-Me-6-PY and N-Me-4-PY, ultimately ameliorating hepatic steatosis." (PMID 39154362, 2024). "In contrast, pharmacological inhibition of AOX1 was sufficient to ameliorate the hepatic steatosis and lipid metabolic dysregulation induced by HFD." (PMID 39154362, 2024). "The apparent beneficial effect of peroxisomal β-oxidation in hepatic steatosis is evident in Aox1-null mice that develop severe microvesicular steatohepatitis." (PMID 20300478, 2009). "The importance of peroxisomal β-oxidation in hepatic steatosis is evident in Aox1-null mice, which show high levels of VLCFA in serum and serve hepatic steatosis, steatohepatitis, and hepatocellular carcinoma." (PMID 20300478, 2009). "After 6 weeks, hepatic steatosis improved in the TRF group, with decreased expression of aldehyde oxidase 1 (AOX1), a key enzyme involved in nicotinamide (NAM) catabolism, which mediates de novo lipogenesis and fatty acid uptake through the production of pro-steatotic metabolites." (PMID 39851512, 2025).
pancreatic cancer (4 papers, 2012 to 2024). "High levels of AOX1 are associated with better prognosis of bladder, renal, and pancreatic cancers, whereas high NMNAT1 expression is associated with poor survival in cancer patients with hepatocellular carcinoma." (PMID 38254798, 2024). "Surprisingly, in previous studies, it has been proved that all of our defined switch genes, including Lamc2, Klk1, Nqo1, Aox1, Tspan1, and Cxcl12, are closely associated with the pancreatic cancer’s progression." (PMID 35180880, 2022). "Our investigation was performed in the Drug Bank database and showed that some drugs, including Peroxisomal acyl-coenzyme A oxidase 1 and Methocarbamol, are designed for Aox1 and Tspan1, as therapeutic anti pancreatic cancer targets, respectively." (PMID 35180880, 2022). "Interestingly, the central roles of Nqo1, Aox1, and Cxcl12 are demonstrated in pancreatic cancer." (PMID 35180880, 2022). "Reduced AOX1 protein expression in chronic pancreatitis and an absence of AOX1 protein expression in pancreatic cancer have been reported." (PMID 23119026, 2012).
Clear Cell Renal Cell Carcinoma (3 papers, 2021 to 2025). "have previously reported that AOX1 is downregulated and functions as a tumor suppressor gene in clear cell Renal Cell Carcinoma (ccRCC) and PCa." (PMID 37583929, 2023).
hepatocellular carcinoma (3 papers, 2012 to 2024). A malignant tumor that arises from hepatocytes. "In addition, decreased AOX1 protein expression was detected in hepatocellular carcinoma and this deregulation of AOX1 expression was associated with tumor stage and metastatic status." (PMID 23119026, 2012).
ovarian carcinoma (3 papers, 2020 to 2021). A malignant neoplasm originating from the surface ovarian epithelium. "In ovarian cancer, AOX1 was shown to be one of the top downregulated genes, and AOX1 knockdown in ovarian cancer cells, OVCAR-3 and CAOV-3, inhibited apoptosis." (PMID 34073600, 2021). "In our study, several DEGs, including WFDC2, INAVA, and AOX1, in ovarian cancer revealed by our meta-analysis have been validated to potentially participate in ovarian cancer development and progression." (PMID 33135729, 2020). "Gene functional analysis demonstrated that up-regulated WFDC2 and INAVA promoted ovarian cancer cell migration, WFDC2 enhanced cell proliferation, while down-regulated AOX1 was functional in inducing cell apoptosis of ovarian cancer." (PMID 33135729, 2020). "Collectively, these data suggested a role for AOX1 in modulating cell death of ovarian cancer." (PMID 33135729, 2020). "Although the mechanism underlying which AOX1 functions in ovarian cancer has not been elucidated, the therapeutic value for AOX1 is still worth further exploration." (PMID 33135729, 2020). "However, only AOX1 of top five down-regulated genes was verified to be decreased in expression for expanding sample of ovarian cancers, with that of REEP1, BNC1, HAND2, and GSDME unchanged." (PMID 33135729, 2020). "In this study, we found that knockdown of AOX1 in ovarian cancer cells inhibited cell apoptosis." (PMID 33135729, 2020). "However, the roles for AOX1 in ovarian cancer have not been addressed." (PMID 33135729, 2020).
meningioma (2 papers, 2015 to 2025). A generally slow growing tumor attached to the dura mater. "It was noted that most of the oxidative stress-related genes presented differential expression between high-grade and low-grade meningiomas, especially AOX1, FOXM1, GPX3, PRNP, and SEPP1." (PMID 41050085, 2025). "When comparing meningiomas with metastases, the two genes that demonstrated the highest mRNA levels, namely AOX1 (M = 12.81) and GSTM3 (M = 7.89) also differed statistically significantly between the two groups (UAOX1 = 5, p = 0.001, r = -0.61 and UGSTM3 = 8, p = 0.002, r = -0.57, respectively)." (PMID 26580399, 2015). "Oxidative stress-related genes such as AOX1, FOXM1, GPX3, PRNP, and SEPP1 were differentially expressed between high- and low-grade meningiomas." (PMID 41050085, 2025). "This study further experimentally validated the key oxidative stress-related genes: AOX1, FOXM1, GPX3, PRNP, and SEPP1 in human meningeal cells (HMC) and two meningioma cells (CH-157MN and IOMM-Lee)." (PMID 41050085, 2025).
Alzheimer disease (1 paper, 2020). A progressive, neurodegenerative disease characterized by loss of function and death of nerve cells in several areas of the brain leading to loss of cognitive function such as memory and language. "AOX1 gene has a previously reported GWAS trait “Late-onset Alzheimer’s disease”37." (PMID 33303834, 2020).
astrocytic tumor (1 paper, 2015). A glial tumor of the brain or spinal cord showing astrocytic differentiation. "In our study, meningeal tumors had higher AOX1 expression levels, compared with astrocytic tumors, both in gene and protein analysis." (PMID 26580399, 2015).
astrocytomas (1 paper, 2015). "A correlation between the gene expression and the protein product was observed for AOX1, GSTP1 and GSTM3 in astrocytomas." (PMID 26580399, 2015). "In astrocytomas, when examining whether WHO-tumor-grade correlates with gene- or protein-expression levels, we found that higher tumor grades were associated with a decreased protein expression for AOX1 and CYP1A1 (data not shown)." (PMID 26580399, 2015).
cervical cancer (1 paper, 2021). A primary or metastatic malignant neoplasm involving the cervix. "More than half of invasive cervical cancers are characterized by deletions of 2q33-q37, and the AOX1 gene is located in 2q33.1 in the human genome." (PMID 34290740, 2021).
chronic kidney disease (1 paper, 2020). Impairment of the renal function secondary to chronic kidney damage persisting for three or more months. "Whereas plasma concentrations of 2Py are reported to increase progressively with chronic kidney disease stages, those of N1-MN are suggested to be less sensitive to kidney function because of the contribution of AOX1 to N1-MN clearance." (PMID 32041099, 2020).